CD40 (CD40 molecule)
Diseases named in the same sentence as CD40 in open-access papers (continued):
Sharing a sentence is not in itself a finding about the gene and the disease.
tumor (continued). "AZD8055/CD40 agonistic antibody significantly increased tumor infiltration by activated CD8+ cells, dendritic cells and macrophages compared to either treatment alone." (PMID 33802831, 2021). "Mice were divided into groups based on equal palpable tumor size 9 days after tumor inoculation and vaccinated with either palmitoylated or unmodified constructs supplemented with adjuvant (agonistic CD40 Ab)." (PMID 34141869, 2021). "CD40 agonism combined with gemcitabine/nab-paclitaxel reduced tumor growth more effectively than either modality alone." (PMID 33804039, 2021). "Next, to assess the in vitro effects of C4BPA on tumor cell proliferation that are exerted via CD40, we examined PDAC cell proliferation with CD40 knockdown." (PMID 34167573, 2021). "Other co-stimulatory receptors include OX40, CD137 (4-1BB), CD27 and inducible T cell co-stimulator (ICOS) on T cells and CD40 on APCs or tumor cells." (PMID 34439292, 2021). "In xenograft models, the antibody reduced tumour growth and increased CD40 expression on tumour tissue." (PMID 33430146, 2021). "Similar to the findings observed in the genetically induced GBM model, pro-CD40 and anti-IL-6 monotherapy showed limited and moderate therapeutic effects on tumor growth and animal survival, respectively." (PMID 34103524, 2021). "To understand the cellular mechanisms involved in the αCD40-induced CD8+ T cell hypofunction, we performed FACS analysis of tumor-infiltrating immune cells that express the CD40 molecule." (PMID 34226552, 2021). "Stromnes and colleagues also provided direct evidence that induction of CD40 on TAMs significantly increased the number of proliferating and GramzymeB+ T cells and decreased tumor cell survival in mice." (PMID 34771482, 2021). "Second, CD40 agonists can directly activate macrophages to infiltrate and deplete tumor stroma, converting ‘cold’ tumors into ‘hot’ tumors." (PMID 33392713, 2021). "Several pre-clinical studies have demonstrated the anti-tumor activity of CD40 agonism and chemotherapy." (PMID 33804039, 2021). "On certain malignant cells, CD40 activation on tumor cells themselves can trigger apoptosis and result in inhibition of tumor growth." (PMID 33804039, 2021). "Our data suggest that Poly6 treatment enhances the production of Tip-DCs and their recruitment into the tumor microenvironment, resulting in effective CD8 T cell-mediated tumor rejection, likely via CD40 activation." (PMID 33499256, 2021). "It is important to note that our studies assessing a role for MMPs in mediating anti-CD40 toxicity were conducted in tumor-free mice." (PMID 34101617, 2021). "CD40 expression is found in the tumor microenvironment, in APCs including dendritic cells, B cells, macrophages, and monocytes and in some solid tumor cells including lung, breast, kidney, and bladder." (PMID 34765538, 2021). "Targeting immune cells is important; indeed, the combination of a CD40 agonist and a PD-1 antagonist MAb exerts anti-tumor effects, which are manifested through tumor infiltration by IFNγ-, Granzyme B-, and TNFα-secreting effector T cells." (PMID 34439378, 2021). "Of note, the combination of a CD40 agonistic monoclonal antibody with PD-1 or CTLA-4 inhibition synergistically induced an anti-tumour immune response resulting in tumour regression in another mouse model of PDAC." (PMID 34439389, 2021). "Stimulation of CD40 on DC enhances their tumor antigen cross-presentation and provides activation signals that mediate effective T cell priming." (PMID 33948686, 2021). "This reversal of tumour desmoplasia makes CD40 an attractive target for multiple therapeutic strategies in PDAC." (PMID 34439389, 2021). "Mounting evidence has demonstrated the efficacy of mannan-BAM, Toll-like receptor (TLR) ligands, and anti-CD40 monoclonal antibodies (MBTA) vaccines in generating an anti-tumor response in solid tumors." (PMID 33810617, 2021).
tumor (continued). "These promising preclinical studies led to numerous clinical trials utilising soluble CD40L or CD40 agonistic antibodies, which demonstrated modest anti-tumour responses thus far." (PMID 34960140, 2021). "CD40 stimulation is known to mediate anti-tumor immunity by inducing a CD8+ T cell response via DC activation." (PMID 34226552, 2021). "Tumor-infiltrating monocytes and macrophages demonstrated increased expression of PD-L1 after treatment with anti-CD40, which is one of the tumor-induced mechanisms for immune suppression." (PMID 33804039, 2021). "Some studies have reported that CD40 activation on B cells can promote anti-tumor effects by providing support to already existing T cell immunity or by functioning as potent APCs and generating effector T cell activity." (PMID 33804039, 2021). "Neutralization of IL-6 or combination treatment of CD40 agonist and Flt3 ligand rescued cDC1 abundance, leading to the control of tumor outgrowth." (PMID 34290984, 2021). "In this study, we consistently observed high expression of both HLA-DR and CD40 by most tumor-infiltrating B cells, as well as CD80, CD83, and CD86 expression by a subset of B cells." (PMID 33763071, 2021). "The CD40L/CD40 system, in addition to its immunological effect, can limit tumor growth by increasing the apoptosis of tumor cells." (PMID 34441316, 2021). "Previous studies have reported the requirement of CD40/CD40L activation of tumor DCs for effective antitumor T cell therapy." (PMID 34912334, 2021). "In this regard, in PDA models, combining chemotherapy with CD40 agonists, presented the infiltration process of T cell and neoantigen-specific response and tumor suppression." (PMID 33494834, 2021). "Our further work identifies a role of CD40 for tumor resistance to anti-IL-6 and checkpoint blockade treatments." (PMID 34103524, 2021). "As multiple cells in the tumor stroma, such as the infiltrating immune cells, express CD40 and 4-1BB, immunotherapies targeting CD40 and 4-1BB have gained growing interest." (PMID 34367111, 2021). "Depletion of host CD8+ and CD4+ T cells prior to treatment with the combination of a CD40 agonist and gemcitabine abrogated their efficacy on tumor growth, demonstrating a role for T cells in the therapeutic response." (PMID 33503832, 2021). "Specifically, CD11b+Gr1+ myeloid cells and reactive oxygen species are identified as mediators of transaminitis induced by anti-CD40 as monotherapy in tumor-bearing mice." (PMID 34101617, 2021). "The CD40 pathway has been demonstrated to be a key regulator of cytokine production, including IL-2, and anti-tumor immune response." (PMID 34830445, 2021). "On the other hand, CD8+ T cells activated by Tip-DCs, via activated CD40, can induce tumor progress suppression via cytotoxic T lymphocyte responses." (PMID 33499256, 2021). "Twelve of the fifteen CD40 CpG probes show a significant difference in methylation between the normal and tumor samples." (PMID 33963293, 2021). "Several preclinical studies have then followed to demonstrate the efficacy of anti-CD40 therapy in stimulating TAMs and resulting in tumor regression and improvement of chemotherapy, anti-angiogenic therapy and ICI efficacies in different tumor models." (PMID 34572939, 2021). "In a similar study, CD40 agonism and gemcitabine-induced macrophage-dependent anti-tumor immunity in KPC tumors." (PMID 33804039, 2021). "The use of CD40 agonists is an attractive approach, particularly with immunotherapy approaches involving the use of tumour antigen." (PMID 34960140, 2021). "In this regard, tumor-derived CXCL1, a ligand for CXCR2, has been implicated as a mechanism of resistance to CD40 immunotherapy." (PMID 33497362, 2021). "CD40L-CD40 interaction triggered activation of tumor-adjacent APC and increased expression of costimulatory molecules such as CD40, CD86 and major histocompatibility complex (MHC) class II." (PMID 34809678, 2021).
tumor (continued). "The availability of CD40L on tumor-infiltrating T cells support our proposed model of CD40-dependent and Tc-dependent immunogenic cell death of tumor cells." (PMID 34092233, 2021). "In accordance with these findings observed in BM-derived Mφs, flow cytometry analysis showed that IL-6 substantially stimulated CD40 expression in tumor-derived Mφs." (PMID 34103524, 2021). "Changes of CD40 agonist antibody to tumor microenvironment can improve the blocking response to PD-L1 in PC mouse model." (PMID 33754011, 2021). "CD40 agonist antibodies induce tumor regression in mouse models of pancreatic cancer as a single-agent and when combined with ICI." (PMID 33392713, 2021). "We identify a Stat3/HIF-1α-mediated axis, through which IL-6 executes an anti-tumor role to induce CD40 expression in Mφs." (PMID 34103524, 2021). "The results showed CD40 agonist induced T cell immune response both at the tumor site and systemically in those early-stage PDA patients." (PMID 34290984, 2021). "The developed drug carrier can specifically target DCs and tumor cells by modified anti-CD40 and anti-PD-L1." (PMID 34541546, 2021). "Agonistic CD40 antibodies can mimic the binding of CD40L to CD40 and initiate downstream signaling that induces anti-tumor immunity." (PMID 33804039, 2021). "A cold tumor can be converted to a “hot tumor” by cisplatin-based chemotherapy, radiotherapy, DC activators (such as agonist CD40 antibodies), and T-cell agonists (such as OX40 or CD137 antibodies)." (PMID 35052695, 2021). "At days 7, 17, and 24, mice implanted with tumor at day 0 were vaccinated with anti-CD40 11B6-CD40L-Doc, anti-CD40 11B6-Doc, IgG4-CD40L-Doc, and non-targeting IgG4-Doc non-covalently linked to human Coh-Cyclin D1." (PMID 35095862, 2021). "CD4+ T cells can also provide help to B cells via CD40/CD40L and p-MHC II/TCR interactions which drive antibody responses to tumor-associated antigens." (PMID 33708224, 2021). "Preclinical mouse models have provided significant rationale for the clinical development of CD40 agonist antibodies as single agent therapies or in combination with standard of care in a variety of tumor types." (PMID 33392713, 2021). "In particular, in cancer, CD40 can license DCs to promote anti-tumour T cell activation and re-educate macrophages, from M2 state to M1 state, leading to fibrosis degradation and tumour regression." (PMID 33544155, 2021). "Garris and coworkers also demonstrated that the intravesical delivery of anti-CD40 antibody induces local anti-tumor activity in a BCG-unresponsive BCa model." (PMID 34572939, 2021). "For almost a decade, CD40 agonist antibodies have been investigated clinically in a range of tumor types with compelling initial results." (PMID 33392713, 2021). "Our data indicated that the triple treatment almost completely blocked tumor growth during the therapy window and, to a lesser extent, combination therapy with IL-6 neutralization and CD40 stimulation markedly reduced tumor growth." (PMID 34103524, 2021). "We have shown a close correlation of the CD40/CD40LG axis with type-I anti-tumor T-cell responses in cancer." (PMID 34758832, 2021). "Early studies in the spontaneous KPC model demonstrated that activation of CD40, a receptor broadly expressed by immune cells, can mediate tumor regression in a T cell-independent, macrophage-driven manner." (PMID 33503832, 2021). "Specifically, chemotherapy when given prior to anti-CD40 is thought to elicit an immunogenic form of tumor cell death and the release of tumor antigens for presentation by APCs, which, when subsequently activated via CD40, prime tumor-specific T cells." (PMID 34101617, 2021). "Here we develop a dual-targeting anti-IL-6 and pro-CD40 strategy to reverse Mφ-mediated tumor immunosuppression and to overcome primary tumor resistance to immune checkpoint blockade in GBM." (PMID 34103524, 2021).
tumor (continued). "In the KPC GEMM model, the combination of a CD40 agonist and gemcitabine induced tumor regression in 30% of tumor-bearing mice, similar to the objective response rate in patients." (PMID 33503832, 2021). "The importance of signaling of CD40/CD40L has been demonstrated in a variety of tumor models, and activation of CD40 affects multiple innate immune cells, providing the promise of harnessing CD40 as a therapeutic target in cancer." (PMID 33804039, 2021). "We found that tumor endothelial cells from agonistic CD40 mAb treated tumors upregulated biological processes such as “inflammatory response”, “response to IFNγ”, “positive regulation of leukocyte chemotaxis” and “positive regulation of TNF production”." (PMID 32231867, 2020). "Lastly, we investigated the effect of CD40 agonistic antibody on the tumor-infiltrating monocyte-derived cells during αPD1 ICB." (PMID 32690667, 2020). "While some studies suggest the involvement of CD40 in promoting MCL tumor cell proliferation, others debate the potential role in growth arrest." (PMID 33287742, 2020). "One method to potentially maximize the engagement of tumor-residing cDC1s is providing CD40 signaling." (PMID 33110069, 2020). "MoDCs in the tumor expressed the highest level of CD40, although expression can also be found on migratory cDCs in lymph nodes." (PMID 32690667, 2020). "Here, IL‐15 caused a significant increase in the number of CD103+ DCs in the tumor while this was significantly lower in the groups following treatment with CD40 agonist." (PMID 32821382, 2020). "Our results demonstrate that tumor endothelial cells contribute to immunosuppressive feed-back loops in response to agonistic CD40 mAb therapy, which restrict the response to immunotherapy through IFNγ-driven expression of IDO1 that inhibits T-cell activation." (PMID 32231867, 2020). "In summary, we show here that the combination of IL‐15 and CD40 agonist therapy has profound anti‐tumor activities and combining both agents leads to significant synergistic effects." (PMID 32821382, 2020). "It is highly likely that this feedback is not limited to CD40-stimulating immunotherapy, but would be induced by other treatments that induce tumor localized T-cell interferon production such as checkpoint-inhibitor therapy or CAR T cells." (PMID 32231867, 2020). "MEKi have also been shown to not inhibit dendritic cell priming by T-cells and to promote synergistic anti-tumor immunity when combined with an immunostimulatory CD40 agonist." (PMID 33245731, 2020). "Altogether, these data indicate that the MEKi/CD40 Ab regimen is more effective, because it increases both the activity of tumor-infiltrating T cells and the magnitude of the T cell response (see further below)." (PMID 32358491, 2020). "Despite acting as a T-cell activation pathway, CD40 activation does exert its antitumor mechanism by reactivating macrophages to change the immune status of the tumor microenvironment." (PMID 33505964, 2020). "Anti-CD40 therapy inhibits tumor growth and induces APC maturation to promote antitumor response, with several ongoing clinical trials." (PMID 32244756, 2020). "Early phase trials regarding CD154 gene transfer have shown various cellular consequences, including cytokine production and enhanced Fas-mediated tumor apoptosis, following CD40 ligation." (PMID 32256143, 2020). "Hereby, we show that the tumor endothelial cells up-regulate IDO1 upon CD40-stimulating immunotherapy in response to increased IFNγ-secretion by T-cells, revealing a novel immunosuppressive feedback mechanism whereby tumor vessels limit T-cell activation." (PMID 32231867, 2020). "With chemotherapy or radiation therapy, CD40 antibody can produce T-cell dependent tumor regressions." (PMID 33304355, 2020). "Unexpectedly, we found that CD25+FoxP3+ Tregs were significantly increased within the tumor microenvironment when agonistic CD40 mAb therapy was combined with epacadostat." (PMID 32231867, 2020).
tumor (continued). "Overall, agonist anti-CD40 improves T cell functionality and synergizes with other immunotherapies to improve the T cell anti-tumor response." (PMID 33584701, 2020). "The activation status of DCs, assessed as upregulation of CD86, CD80 and CD40 when co-cultured with virus-infected tumor cells, was both virus and cell line-dependent, with some degree of activation in all cases." (PMID 31969562, 2020). "Agonistic CD40 can drive the priming of a robust anti-tumor T cell response dependent on IFN-γ and Batf3 expression, while CD40 ligation on TAMs drives a tumoricidal response that depletes the stroma in the TME." (PMID 33597954, 2020). "CD40-stimulating immunotherapy can elicit potent anti-tumor responses by activating dendritic cells and enhancing T-cell priming." (PMID 32231867, 2020). "In recent years, CD40 activation can strengthen the immune responses induced by various vaccines and can generate long-time anti-tumor effects." (PMID 32536922, 2020). "Previous studies have suggested that CD40-activated macrophages can inhibit tumor growth due to IFN-γ production, indicative of a classically-activated macrophage phenotype." (PMID 35582441, 2020). "Although single-agent MEKi treatment results in transient tumor stasis in this model, prolonged stasis and tumor rejection was only achieved in MEKi/CD40 Ab-treated mice." (PMID 32358491, 2020). "The expression of these markers are particularly undesirable on cells destined for allogeneic therapies, as they are all expressed on antigen presenting cells of the immune system, with CD40 also being found on tumour cells." (PMID 32596691, 2020). "In our study, it's worth noting that CD40 vaccine can only inhibit larger tumor (>1 cm3) for several days but can completely eliminate smaller tumor (<0.2 cm3), what's more, CD40 vaccine can suppress the growth of tumor in early stage until it disappears." (PMID 32536922, 2020). "Replacement of the hinge region with that of IgG3 completely eliminated the anti-tumor activity of the anti-CD40 antibody, although both the CD40 and the FcγR binding affinity were retained." (PMID 32370812, 2020). "We observed a strong synergistic anti-tumor effect of MEKi/CD40 Ab, which was accompanied by prominent changes in immune-cell infiltrate in the TME." (PMID 33024933, 2020). "The combination of intratumoural MPL and agonistic anti-CD40, which is known to activate macrophages, enhanced macrophage-induced killing of tumour cells, resulting in a significant increase in anti-tumour activity in mice compared to either treatment alone." (PMID 33352882, 2020). "To obtain an unbiased view on the mechanism of action of MEKi and anti-CD40 Ab in our tumor models, we performed transcriptome analysis of tumors isolated from mice undergoing treatment." (PMID 32358491, 2020). "Here, the authors show that combining MEK inhibition with an agonist anti-CD40 immunostimulatory antibody improves antitumor treatment by inducing immunogenic changes in the tumor microenvironment." (PMID 32358491, 2020). "Early mechanistic studies also demonstrated that CD40 stimulation can enhance the efficacy of tumor antigen vaccination, induce activation of endogenous CD4+ T cells and reverse cytotoxic T cell tolerance." (PMID 33101304, 2020). "And a tumor-targeting CD40 bispecific compound, ABBV-428, has been applied for clinical immunotherapy." (PMID 32536922, 2020). "A further pathway analysis demonstrated that LAPTM5 mediates these tumor-suppressing and temozolomide-sensitizing effects by the inhibition of CD40-induced NFκB pathway activation." (PMID 32582531, 2020). "The increase in IDO1 in B16-F10 tumor endothelial cells treated with agonistic CD40 mAb correlated with IFNγ expression in the tumor tissue." (PMID 32231867, 2020). "Alternatively, CD40 antibodies have been combined with IL-2 immunotherapy as a strategy to induce tumor-specific T cell immunity in tumor models of renal cell adenocarcinoma or Lewis lung carcinoma." (PMID 35582441, 2020).